LINC01143 (long independently transcribed non-coding RNA 1143)
Gene: Long non-coding RNA gene on chromosome 2 (70,887,850 to 70,889,989, forward strand). Ensembl gene ENSG00000237751.
Diseases named in the same sentence as LINC01143 in open-access papers:
LINC01143 is named in the same sentence as 2 diseases in open-access papers, as found by Europe PMC text mining. Sharing a sentence is not in itself a finding about the gene and the disease.
LINC01143 shares sentences with these, for which no sentence is quoted: cancer (1 paper); lung adenocarcinoma (1).